LEF1 (lymphoid enhancer binding factor 1)
Diseases named in the same sentence as LEF1 in open-access papers (continued):
Sharing a sentence is not in itself a finding about the gene and the disease.
tumor (continued). "We confirmed that Wnt1-positive populations mostly overlapped with LEF1-positive subpopulations in tumor xenografts." (PMID 26202299, 2015). "Several studies found effects of LEF-1 expression on the degree of malignancy in neoplastic diseases." (PMID 25805670, 2015). "Our findings imply that sebaceous tumours differ with respect to the regulation and activity of the K14- and K15-promoter sequences driving the expression of mutant Lef1 in the different mouse models." (PMID 25608467, 2015). "A number of Notch target genes were consistently overexpressed in CYLD defective tumours, including LEF1, HEY1 and NOTCH1." (PMID 25565632, 2014). "Nuclear HES1 was seen to be increased in CYLD defective tumours, but the difference from control epidermis was smaller than for LEF1 and RUNX1 (p = 0.027)." (PMID 25565632, 2014). "Forty five days after tumor cell injection, LEF1 knockdown-tumor xenografts showed a reduction of tumor growth compared to control-shNC tumor xenografts." (PMID 24098538, 2013). "In this study, we reveal that IGF2BP1 enhances mesenchymal-like cell properties in tumor-derived cells by promoting the expression of the transcriptional regulators LEF1 and SLUG (SNAI2)." (PMID 23677615, 2013). "LEF1 protein containing β-catenin binding domains can regulate cell proliferation and invasion of tumor cells." (PMID 24098538, 2013). "Nude mouse xenograft assay showed that LEF1 knockdown suppressed tumor formation and growth in vivo." (PMID 24098538, 2013). "Actβ-Cat;PtenF/F;PBCre prostates have higher levels of active non-phosphorylated β-Catenin than Pten null prostates and show a clear induction of LEF1, indicating these tumours have an increase in β-Catenin mediated transcription." (PMID 23300485, 2013). "Strikingly, we observed that IGF2BP1-facilitated modulation of tumor cell migration involves IGF2BP1-directed control of LEF1 and SNAI2 expression." (PMID 23677615, 2013). "The Tcf1−/− tumor samples were clearly distinguished by factors involved in the Wnt-signaling pathway, Axin2, Lef1, and Tnfrsf19, or in the Notch signaling pathway, Deltex1 and Hes1." (PMID 23185135, 2012). "Although Lef1 expression was higher than normal inactive endometrium in grade 3 tumor samples, it was lower than that in grade 1 and 2 tumors." (PMID 22792274, 2012). "In nude mice, the formation of neovasculature as well as an increase in tumor volume were inhibited by the short isoform of LEF-1." (PMID 22639890, 2012). "The thymi of the Tcf1+/− control mouse and the two Tcf1−/− tumor mice displaying high Wnt activity were further examined for the RNA expression levels of Lef1 and Hes1." (PMID 23185135, 2012). "In all tested tumor samples, the expression level of Lef1 was increased compared to thymocytes of control mice." (PMID 23185135, 2012). "We next examined levels of Lef1 RNA expression across the range of tumor subtypes: endometrioid, papillary serous, and MMMT." (PMID 22792274, 2012). "Analysis of the Tcf1−/− tumor samples (RNA and protein) revealed that the normal ratio of long over short isoforms for Lef1 was altered in favor of the long isoform of Lef1, which mediates transcription of Wnt-β-catenin target genes." (PMID 23185135, 2012). "While the Lef1 gene was moderately upregulated in transgenic and tumor cells, Tcf7 showed significant upregulation in tumor." (PMID 21464922, 2011). "In sum, the phosphorylation of β-catenin at Ser552 by AKT1 increases nuclear translocation and retention, enhancing Tcf4/Lef1 complex transcriptional activity to promote tumor cell invasion and stem cell migration." (PMID 20858269, 2010).
tumor (continued). "Ser552 phosphorylation results in β-catenin translocation from the cytosol into the nucleus, increasing Tcf4/Lef1 transcriptional activity and promoting tumor cell invasion." (PMID 20858269, 2010). "When overexpressed LEF-1 leads to an enhanced tumour cell invasiveness and induces epithelial to mesenchymal transition." (PMID 21092222, 2010). "TCF4 and LEF-1 expression was found to be heterogeneously distributed throughout the tumours, which is in support with the fact that individual tumours are organized hierarchically." (PMID 21092222, 2010). "Both transcription factors were found mainly to be heterogeneously distributed throughout the tumours with expression of LEF-1 and TCF4 in cells of the invasive front in the majority of cases." (PMID 21092222, 2010). "This assumption seemed to be in accordance with studies showing that LEF-1 enhances tumour cell invasiveness and induces an epithelial to mesenchymal transition." (PMID 21092222, 2010). "Cellular distribution pattern of LEF-1 protein was compared between peritumor cells and tumor cells of HBsAg positive tissues." (PMID 19402906, 2009). "Specifically, the expression levels of HBsAg, LEF-1, cyclin D1 and c-myc were studied in tumor cells and peritumor cells from the same patient." (PMID 19402906, 2009). "LEF-1 protein was located either exclusively in the nucleus or both in the nucleus and cytoplasm of tumor cells, whereas in peritumor cells LEF-1 was located predominantly in the cytoplasm." (PMID 19402906, 2009). "By real-time PCR, the expression levels of LEF-1 downstream effector genes cyclin D1 and c-myc were higher in peritumor cells compared to that of the tumor cells." (PMID 19402906, 2009). "Results showed that compared to that of normal liver tissues by real-time PCR, both 38 kDa truncated isoform and 55 kDa full-length LEF-1 were markedly increased in tumor cells and peritumor cells." (PMID 19402906, 2009). "The 38 kDa truncated isoform of LEF-1 was significantly up-regulated in tumor cells compared to that in the peritumor cells, while the 55 kDa full-length LEF-1 did not exhibit changes between tumor and peritumor cells." (PMID 19402906, 2009). "In the peritumor cells LEF-1 was predominantly located in the cytoplasm, while in the tumor cells LEF-1 was located exclusively in the nucleus or both in the nucleus and cytoplasm." (PMID 19402906, 2009). "As we have previously observed that expression of HBsAg initiated transfer of LEF-1 from the cytoplasm into the nucleus, in this study, we further identified that the transfer of LEF-1 into the nucleus also occurred in tumor cells." (PMID 19402906, 2009). "The estimated molecular weights of the proteins expressed in these tumours were as expected: 92 kDa for β-catenin, 46–48 kDa for GSK3β and approximately 55–60 kDa for Lef-1." (PMID 14520463, 2003). "FOXP1 was highly expressed in tumor tissues, as well as LEF1 and OCT4, which are markers of CSCs." (PMID 40169859, 2025). "LEF1 is known to facilitate epithelial–mesenchymal transition (EMT), a hallmark of cancer progression characterized by increased migration and invasion of tumor cells." (PMID 39851951, 2025). "Previous bioinformatics analysis indicated that LEF1 may promote EMT progression in drug-resistant tumor cells." (PMID 40810004, 2025). "High infiltration by CD3+ T cells with high LEF-1 expression was present in 7 tumours." (PMID 40130164, 2025). "To examine whether LEF1 expression in exp‐CAF 544 cells correlates with their ability to promote tumor proliferation, we employed a xenograft model using immunodeficient NOG mice." (PMID 39887653, 2025). "Low numbers of CD3+ T cells in combination with low LEF-1 expression was present in 7 tumours." (PMID 40130164, 2025). "Third, whether additional nuclear substrates beyond LEF1 contribute to USP30's tumor suppressive functions warrants systematic identification." (PMID 41306556, 2025).
tumor (continued). "Importantly, we found HLA-B, HLA-E, and PSMB10 all related to antigen presentation to be enriched among down-regulated genes in tumours with high LEF-1 expression suggesting an adverse impact of Wnt/β-catenin pathway on tumour recognition by immune cells." (PMID 40130164, 2025). "Thus, in comparison with β-catenin, LEF1 has higher sensitivity, harbors clean, clear staining, and is easy to evaluate the tumor border, making it a better marker for diagnosing SPN." (PMID 39881334, 2025). "have demonstrated ACCs with an activating CTNNB1 mutation to exhibit higher expression of LEF-1 compared to non-tumour adrenal samples and ACCs without CTNNB1 mutation." (PMID 40130164, 2025). "Patients with high LEF-1 expression had a significantly higher tumour stage at diagnosis." (PMID 40130164, 2025). "We propose that incorporating LEF1 and HNF4A into diagnostic staining panels could enhance tumor diagnosis, enabling a more precise tumor subtyping and correlations between molecular profiles of tumor and disease prognosis." (PMID 39567475, 2024). "In addition, consistent with tumor tissue stainings, HNF4A and LEF1 marked fetal and embryonal tumor organoids, respectively." (PMID 39567475, 2024). "Overall, we confirmed the existence of two distinct tumor subpopulations expressing either HNF4A or LEF1 and found that these two markers could distinguish tumor subpopulations better than β-catenin staining alone." (PMID 39567475, 2024). "In addition, the dichotomous expression pattern of the transcription factors HNF4A and LEF1 allows for a clear distinction between the fetal and embryonal tumor cells." (PMID 39567475, 2024). "Furthermore, we demonstrated a mutually exclusive expression pattern of HNF4A and LEF1 in a cohort of tumor tissues by IF staining." (PMID 39567475, 2024). "Therefore, we will expand the characterization of our series of tumors by studying LEF1 involvement in tumor development." (PMID 39099687, 2024). "The change in Wnt effectors is likely an important driver of tumour-specific gene expression, as TCF/LEF binding motifs are enriched in tumour-specific active chromatin, and given that Lef1/Tcf7 are mostly transcriptional activators while Tcf7l1 is known to have mainly repressive functions." (PMID 37907668, 2023). "In 2015, Hugo W. at al reported that up-regulation of gene expression of C-MET, down-regulation of gene expression of LEF1, tumor cell-intrinsic CpG site methylation and YAP1 pathway signature enrichment could be associated with acquired MAPKi resistance." (PMID 37568633, 2023). "Furthermore, nude mice injected with VDR-overexpressing SW480 cells revealed suppression of tumour growth and decreased expression of β-catenin, cyclin D1 and LEF-1." (PMID 37046222, 2023). "Notably, LEF1 with disrupted IDR lost its promoting activity on tumor proliferation and metastasis, which can be restored by substituting with FUS IDR." (PMID 37657935, 2023). "Importantly, the most significantly enriched transcription factor motif in tumour-specific H3K27ac regions was LEF1, while TCF7 and TCF7L1 motifs were also highly enriched." (PMID 37907668, 2023). "Furthermore, disruption of IDR in LEF1 abolishes its capacity to promote tumor proliferation and metastasis, whereas substitution with FUS IDR reinstates this promoting activity." (PMID 37657935, 2023). "Our results indicate that only LEF1 WT, but not phase separation-deficient mutant, can promote tumor cell growth by the transcription of downstream target genes." (PMID 37657935, 2023). "Indeed, LEF1 functions as an oncogenic molecule in various tumours; our results demonstrated that its expression was upregulated in OSCC and promoted cancer in vitro and in vivo." (PMID 37553362, 2023). "Therefore, our findings provide insights into a potential mechanism for Wnt-mediated tumor proliferation via LEF1 LLPS." (PMID 37657935, 2023).
tumor (continued). "Previous studies also found that IGFBP2 could accelerate the migration of tumor cells by regulating LEF1 and SNAI2." (PMID 35519620, 2022). "Moreover, it was proved that EMT can be enhanced to boost tumor metastasis by HSF1 combined with LEF1 dependence in BC." (PMID 35964079, 2022). "Given the importance of LEF1 on driving tumor initiation and progression, we surmised that NR4A1 might stimulate PTC tumor aggressiveness through the LEF1 pathway." (PMID 35110542, 2022). "LEF-1 acts like a nuclear anchor, β-catenin can direct interaction with that, providing a molecular mechanism for the transmission of signals to nuclear, driving tumor formation." (PMID 36096860, 2022). "Moreover, the protein levels of LRP5, LRP6, TCF-4, and LEF1 in the tumor were also significantly down-regulated by AR decoction or oxaliplatin treatment in xenograft mice." (PMID 34991661, 2022). "Interestingly, at the IHC level and based on CD10, β-catenin, and LEF-1 positivity, the tumor entity closest to the reported tumors was pancreatic SPN." (PMID 35359182, 2022). "miR-498 attenuates tumor development by repressing LEF1 in OS cells." (PMID 34096776, 2021). "Experimental results indicated that miR-498 could directly target LEF1 in OS cells and that circ_0032463 could abrogate the tumor-inhibitory effect of miR-498 by upregulating LEF1 in OS." (PMID 34096776, 2021). "On the contrary, the tumor weight was largely decreased by the treatment of LEF1 OP‐V1, implying the inhibitory effect of LEF1 OP‐V1 on tumor growth was not caused by the general toxicity of the O'PROTAC in mice." (PMID 34397171, 2021). "The exclusive increase of Cbx3/HP1γ-deficient CD8+ effector T cells in tumors and their subsequent disappearance when Lef1 is ablated suggest that LEF-1 is requisite for their persistence in varied tumor types irrespective of mutational status." (PMID 34721405, 2021). "Thus, both increased proliferation and decreased apoptosis contribute to faster tumor growth in mice with combined deletion of Apc and Lef1." (PMID 34788095, 2021). "LEF1 is generally excessively expressed in malignant tumors and may play a role in tumor growth and metastasis." (PMID 34639214, 2021). "Lef1- and Cbx3-Lef1-deficient mice, in which Tcf7 is not deleted, fail to control tumor growth suggesting that Lef1 function is not redundant." (PMID 34721405, 2021). "Firstly, eleven tumours showed LEF1 positive staining restricted to the invasive front." (PMID 34420090, 2021). "Our finding of extremely low Lef1 expression in ligand-dependent CRCs also argues that Lef1 levels in CRC tumor cells could serve as a biomarker for the identification of patients with CRC who may benefit from WNT ligand inhibition." (PMID 34788095, 2021). "LEF1 could promote tumor cell metastasis by participating in EMT and regulating the intracellular reactive oxygen species (ROS)." (PMID 34957213, 2021). "Pairwise comparison with TCF7, suggests LEF1 in tumor may also be correlated with regulation of cell migration." (PMID 32403323, 2020). "Furthermore, transcripts indicative of angiogenesis are correlated with TCF7L1 in tumor; and transcripts indicative of DNA double-strand break repair and of cell cycle progress with LEF1 in tumor." (PMID 32403323, 2020). "Importantly, among the LEF/TCF genes, our meta-analysis also corroborates a switch from relatively higher TCF7L2 and TCF7L1 expression in normal control to relatively higher TCF7 and LEF1 expression in tumor tissue." (PMID 32403323, 2020). "The overexpression of LEF1 significantly increased tumor growth." (PMID 31296250, 2019). "The inhibition of LEF1 might therefore be a novel therapeutic target to inactivate CSCs and inhibit tumor progression." (PMID 31296250, 2019).
tumor (continued). "Furthermore, we evaluated the role of LEF1 in facilitating the effects of OCT4 on tumor cell EMT, invasion, and migration." (PMID 29974668, 2018). "Moreover, we detected both OCT4 and LEF1 expressions in ESCC tumor specimens and found that the combination of OCT4 and LEF1 was closely related to the surgical outcomes of patients with ESCC." (PMID 29974668, 2018). "Several studies have reported the increased expression of OCT4 and LEF1 in many tumor types." (PMID 29974668, 2018). "This increased expression in cancer suggests that OCT4 and LEF1 might play important roles in tumor proliferation, angiogenesis, invasion, and metastasis." (PMID 29974668, 2018). "In agreement with the in vitro experiments, the LEF1 KD in RMS-13 cells augmented tumor growth." (PMID 27965462, 2017). "Although LEF1 frequently acts as an oncogene, it also can function as a tumor suppressor gene." (PMID 27965462, 2017). "Overexpression of LEF1 has been detected in many tumor entities." (PMID 27965462, 2017). "In cells derived from the same tumor, we demonstrated that the prevalence of LEF1 (high β-catenin expressing cells) or TCF4 (low β-catenin expressing cells) as β-catenin partner for DNA binding, is associated to the expression of two distinct profiles of WNT-responsive genes." (PMID 27175588, 2016). "Thus, normal control of SC proliferation is disrupted by mutant Lef1, thereby allowing uncontrolled propagation of tumour-initiating SCs." (PMID 25608467, 2015). "Moreover, this important observation indicates that the level of oncogene expression by SCs is crucial for tumour initiation and highlights the specific and sensitive role of bulge SCs towards mutant Lef1 function." (PMID 25608467, 2015). "LEF-1 appears to mediate tumor growth and invasion ability in androgen-independent prostate cancer." (PMID 25805670, 2015). "Our experiments address the role of mutant Lef1 in tumour initiation specifically by SCs." (PMID 25608467, 2015). "Thus, our data show that the type of epidermal cell expressing mutant Lef1 impacts on tumour morphology and differentiation profile." (PMID 25608467, 2015). "Thus, inhibition of β-catenin/Lef1 activity in bulge SCs is sufficient to promote sebaceous tumour formation." (PMID 25608467, 2015). "Deregulated LEF-1 expression may also be an important step in the development of neoplastic diseases." (PMID 25805670, 2015). "LEF1 knockdown suppressed tumor formation and growth in nude mice." (PMID 24098538, 2013). "In addition to controlling actin dynamics, IGF2BP1 sustains mesenchymal cell properties and modulates tumor cell migration also through the upregulation of LEF1 and SNAI2." (PMID 23677615, 2013). "Furthermore, LEF1 knockdown reduced tumor cell viability, invasion capacity, MMP2 and MMP-9 expression, but induced apoptosis." (PMID 24098538, 2013). "Whether LEF1 or SNAI2 could recover IGF2BP1 knockdown-induced impairment of tumor cell migration was determined by their stable expression in IGF2BP1-depleted cells." (PMID 23677615, 2013). "Hence, although FN1 and CDH1 are presumably not the key markers involved, these findings supported the view that the role of IGF2BP1 in promoting tumor cell migration and sustaining mesenchymal-like cell morphology involves the upregulation of LEF1 and SNAI2." (PMID 23677615, 2013). "In multivariate analysis, LEF-1 and TCF4 expression were confirmed to be independent predictors of longer respectively shorter overall survival, when considered together with tumour stage, gender and age (risk ratio for LEF-1: 2.66; p = 0.027 risk ratio for TCF4: 2.18; p = 0.014)." (PMID 21092222, 2010).